MIF (macrophage migration inhibitory factor)
Diseases named in the same sentence as MIF in open-access papers (continued):
Sharing a sentence is not in itself a finding about the gene and the disease.
Sepsis (continued). "The aim of this study was to evaluate the association of the MIF-173 G/C SNP and the MIF -794 CATT5-8 microsatellite with severe sepsis compared to healthy blood donors and patients with abdominal surgery but without signs of infection or inflammation." (PMID 19941661, 2009). "Circulating concentrations of MIF were markedly elevated in children and adults who had severe sepsis or septic shock." (PMID 19941661, 2009). "An inverse correlation was demonstrated between MIF and delta max cortisol or the delta max cortisol/albumin ratio in patients with severe sepsis or septic shock." (PMID 20021698, 2009). "The role played MIF has been described extensively in sepsis, in which serum levels of MIF were found to be increased in septic patients and correlated with both disease severity and mortality." (PMID 19558639, 2009). "MIF has been detected in increased amounts in patients with severe sepsis and septic shock and has been demonstrated to be involved in pathogenesis of shock." (PMID 19014537, 2008). "MIF, a pro-inflammatory mediator shown to be upregulated dramatically in a number of tissues in both severe falciparum malaria and sepsis, also accelerates glycolysis, so can be expected to contribute to the hypoglycaemia and hyperlactataemia of both diseases." (PMID 17029647, 2006). "Subsequently, MIF proved to be strongly detectable by immunohistochemistry in systemic, but not cerebral, vascular smooth muscle of fatal African paediatric sepsis and falciparum malaria." (PMID 17029647, 2006). "In a rat model of sepsis, treatment with neutralizing anti-MIF reduced acute inflammation of the heart and improved myocardial dysfunction, providing evidence that MIF inhibition may be beneficial in sepsis-induced cardiomyopathy." (PMID 40092999, 2025). "Therefore, it is crucial to measure plasma MIF concentrations during sepsis diagnosis、 treatment and nurse." (PMID 40595050, 2025). "Similarly, nanobodies targeting MIF have been developed for sepsis treatment, some of which have shown promise." (PMID 40092999, 2025). "Clinical studies have shown that patients with sepsis have high levels of MIF in blood." (PMID 40518584, 2025). "The inhibitors of MIF for sepsis have attracted the attention of a number of researchers." (PMID 40518584, 2025). "CSN6 induces MIF expression in macrophages in an in vitro model of sepsis." (PMID 40595050, 2025). "MIF has the direct pro-inflammatory role in inflammatory diseases, such as sepsis." (PMID 40518584, 2025). "The inhibitors of MIF inhibit the release of inflammatory factors to treat sepsis." (PMID 40518584, 2025). "Further research involving in vivo models, such as examining CSN6 and MIF expression levels in macrophages or monocytes from sepsis and control mice, is essential to fully confirm these findings and establish the therapeutic potential of targeting the CSN6/MIF axis in sepsis." (PMID 40595050, 2025). "Moreover, administration of recombinant MIF significantly enhanced LPS-induced lethality in an experimental model of sepsis, further supporting the role of MIF in the pathogenesis of septic shock." (PMID 40092999, 2025). "Confocal microscopy analysis suggested that CSN6 induces MIF expression in macrophages in an in vitro sepsis model; additional images with a higher number of cells (n = 15 fields with approximately 5–10 cells per field) were analyzed to robustly support this conclusion." (PMID 40595050, 2025). "Moreover, clinical data indicate that MIF is served as a biomarker for the treatment and diagnosis of sepsis." (PMID 40518584, 2025). "It is urgent to discovery a new MIF inhibitor to treat sepsis." (PMID 40518584, 2025). "Interestingly, MIF demonstrated a specific role in the recruitment and accumulation of inflammatory macrophages in an animal model of polymicrobial sepsis." (PMID 38476376, 2024). "Another study revealed that sepsis increased MIF levels in lung tissue relative to the sham group." (PMID 39144689, 2024).
Sepsis (continued). "The levels of MIF in the bloodstream are increased in patients with sepsis and are linked to negative clinical outcomes." (PMID 38745657, 2024). "Nevertheless, while acting as a receptor, Neutrophils connected with plasma cells by up-regulating MIF-(CD74+CD44) (strong) in both sepsis and control group, but connected with CD8+ T cell, NK cell, B cell, and DC by down-regulating MIF-(CD74+CD44) in both sepsis and control group." (PMID 39108261, 2024). "MIF is expressed broadly in different types of human cells and has been related to different human disease, which has emerged as a promising drug target in diseases including sepsis, rheumatoid arthritis, polycystic kidney disease (PKD) and cancer." (PMID 38052787, 2023). "MIF is a crucial factor in the development of sepsis, being involved in the recruitment of inflammatory cells such as macrophages, basophils, neutrophils, and eosinophils to the site of inflammation, resulting in an extensive release of different proinflammatory cytokines such as IL-1β and TNF-α." (PMID 38313162, 2023). "Future studies are warranted to reveal the exact function of renal MIF in sepsis." (PMID 36631486, 2023). "From this point, several studies have been conducted on the role of MIF in sepsis." (PMID 38275363, 2023). "Our results suggest that MIF may exert its effects by binding to various receptors on different cell types in sepsis." (PMID 37919720, 2023). "Therefore, it can be concluded that MIF has emerged as a potential biomarker and therapeutic target in sepsis." (PMID 38275363, 2023). "The impact of lacking these regions was suggested in a sepsis model, using MIF-deficient and DDT-deficient mice." (PMID 36672343, 2023). "Ticagrelor pretreatment led to decreased lung tissue levels of MIF compared to the sepsis group." (PMID 37675176, 2023). "MIF functions in innate immunity and levels are elevated in sepsis, autoimmune diseases and cancer." (PMID 36721240, 2023). "Taken together, the abundance of MIF in the bloodstream in sepsis and the decreased estrogen levels in postmenopause can serve as a hypothetical reason why the MIF levels increased in both survivor and nonsurvivor septic females to a greater extent than in males in our study." (PMID 36631486, 2023). "Several studies have shown that MIF mediates inflammatory processes, such as sepsis and cancer." (PMID 36496973, 2022). "Characteristics of MIF make it a potential biomarker of sepsis." (PMID 35165294, 2022). "Finally, high levels of MIF and IL-10 were both found to have bad prognostic value for the fatal outcome of sepsis patients, where high levels of IL-10 were found to have the highest prognostic value." (PMID 35464430, 2022). "Thus, urinary and plasma MIF levels are associated with the development of AKI in patients with acute pyelonephritis, severe sepsis and septic shock, after cardiac surgery or liver transplantation." (PMID 35563296, 2022). "According to previous studies, we hypothesized that up-regulation of MIF in sepsis-induced AKI makes a renal damage effect and promotes NLRP3 inflammasome activation to aggravate cell pyroptosis." (PMID 35165294, 2022). "Indeed, a study reported that a panel of fully humanized anti-MIF antibodies directed against the binding epitopes within amino acids 50-68 or 86-102 of the MIF molecule, were protective in experimental models of sepsis." (PMID 35464430, 2022). "Furthermore, MIF has been involved in the pathogenesis of sepsis, asthma, cystic fibrosis, metabolic diseases." (PMID 33356032, 2021). "In conclusion, blood MIF level is more elevated in systemic inflammation caused by infection (i.e., sepsis) compared to noninfectious causes." (PMID 33850259, 2021). "Similarly, during sepsis or liver transplantation, increased MIF levels appear to aggravate renal damage." (PMID 34540864, 2021).
Sepsis (continued). "A previous study showed that C5a induces MIF production by neutrophils in sepsis, although the exact interaction between C5a and MIF as well as their roles in AAV remain mostly unknown." (PMID 31248381, 2019). "In sepsis, knockout or inhibition of MIF also increased survival rate of mice." (PMID 27409803, 2016). "Moreover, in other settings where there is significant MIF release, such as in sepsis, MIF has shown cardio-depressant properties." (PMID 27335054, 2016). "In addition to sepsis, MIF knock-out (Mif−/−) mice show reduced mortality compared to wild-type mice after Toxoplasma gondii infection, indicating that MIF is also involved in the pathogenesis of infection by this protozoan." (PMID 25821355, 2015). "Several studies have tested MIF inhibitors or MIF blocking antibodies to decrease inflammation in diseases such as sepsis and autoimmune diabetes, and thus, the same approach could be tested in colon cancer." (PMID 24887129, 2014). "Results of that study showed that only the antibody-binding epitopes within amino acids 50–68 or 86–102 of the MIF molecule, the regions forming a β-sheet structure in the MIF oxidoreductase motif, exerted protective effects in models of sepsis or contact hypersensitivity." (PMID 24424397, 2014). "MIF appears to be a promising candidate for the treatment of sepsis in traumatic conditions." (PMID 23251299, 2013). "MIF antibody treatment can preserve the cardiac function of mice in sepsis." (PMID 24371817, 2013). "Conversely, several studies showed that the neutralization of MIF reduced proinflammatory cytokine production, decreased organ injury, and increased the survival rate of mice in different animal models of sepsis, such as endotoxic shock, Escherichia coli injection or CLP." (PMID 23853427, 2013). "Macrophage migration inhibitory factor (MIF) is one of the important factors in sepsis." (PMID 24371817, 2013). "In this study, HS significantly reduced MIF protein expression in myocardium and maintained cardiac function, suggesting that the inhibitory effect on MIF production contributes to the cardioprotection of HS in sepsis." (PMID 24371817, 2013). "Therefore, we suggest that, via suppression of neutrophil infiltration into, myocardium, HS attenuates inflammation-related responses, for example, MIF release by immune cells and NF-κB activation in cardiomyocytes during sepsis." (PMID 24371817, 2013). "The actions of MIF in sepsis pathophysiology have been studied extensively." (PMID 23853427, 2013). "In the 1990s, sepsis was believed to be associated with an exacerbated release of mainly proinflammatory cytokines, such as tumor necrosis factor (TNF)-α, interleukin (IL)-1, IL-6, IL-12, interferon (IFN)-γ, and macrophage migration inhibitory factor (MIF)." (PMID 23853427, 2013). "Of note, MIF levels peaked earlier than those of other inflammatory cytokines and sepsis markers." (PMID 22506003, 2012). "We hypothesise that MIF is an initial proinflammatory mediator during V. vulnificus infection, which is consistent with previous reports on patients with sepsis and endotoxaemic models." (PMID 20939898, 2010). "Not surprisingly, different markers of systemic inflammation (e.g., IL-6) and mediators involved in the redox homeostasis (e.g., TRX1, MIF) are significantly elevated during ongoing sepsis, whereas only IL-6 differed between patients after major abdominal surgery and healthy volunteers." (PMID 20847814, 2010). "This further highlights the potential diverse nature of MIF function during the course of sepsis." (PMID 20169062, 2010). "Previous studies found that serum levels of MIF were related to mortality in sepsis." (PMID 19558639, 2009). "We speculated that the serum MIF concentration might reflect adrenal function in the hypothalamo-pituitary-adrenal (HPA) axis in patients with sepsis." (PMID 20021698, 2009). "Macrophage migration inhibitory factor (MIF) plays an important regulatory role in sepsis." (PMID 19941661, 2009).
Sepsis (continued). "Consequently, we consider that the measurement of the serum MIF concentration in the early phase of sepsis is useful in detecting and even treating inflammatory imbalance and organ failure." (PMID 20021698, 2009). "MIF may play an important role in sepsis as a pro-inflammatory cytokine and an inflammatory modulator, and may be a marker of the severity of the associated adrenal insufficiency." (PMID 20021698, 2009). "Moreover, injection of MIF increased mortality in experimental sepsis, whereas inhibition of MIF decreased mortality, emphasizing the critical involvement of MIF in the pathophysiology of septic shock." (PMID 19558639, 2009). "Macrophage migration inhibitory factor (MIF) is a multifunctional cytokine whose role as an important regulator of immune and inflammatory responses in a number of human diseases, such as sepsis, rheumatoid arthritis, cancer and inflammatory neurological diseases, has been confirmed." (PMID 19284533, 2009). "This suggests that MIF may act to modulate and amplify the response to lipopolysaccharide in sepsis." (PMID 17470266, 2007). "Ten years later, and long before MIF was realised to have functions other than migration inhibition and pathogenicity in sepsis (which its inhibition suppresses, in a realistic model, most impressively), it was the first cytokine described in a malaria infection." (PMID 17029647, 2006). "Since TNF, IL-1, IL-6 and MIF are all highly expressed in falciparum malaria, it can be expected that these cardiac-depressing activities would be acting in this disease as well as in sepsis." (PMID 17029647, 2006). "During the early phase of infection, MIF contributes to pathogen clearance; however, excessive MIF expression may lead to uncontrolled inflammation, exacerbating tissue damage and promoting the development of sepsis and ARDS." (PMID 40718479, 2025). "The relationship between MIF and D-DT/MIF-2 in adipocytes could therefore be inverted in sepsis." (PMID 38275363, 2023). "Therefore, there is an inverse relationship between adipocyte MIF and MIF-2 expression in sepsis, where the downregulation of MIF-2 in AT may increase the polarization of ATRMs toward the M1-like subtype and further drive adipose inflammation." (PMID 38027963, 2023). "Furthermore, Ticagrelor was found to reduce tissue cytokine levels of the lung (IL-1, TNF a, IL-6, F2 isoprostane, GPR 17, MIF) in male mice during CLP-induced polymicrobial sepsis by modulation of pro-inflammatory and oxidative stress cascade signaling pathways." (PMID 37675176, 2023). "Thus, we analyzed how the serum MIF levels changed from the first until the last measurement in each individual patient, and then compared the kinetics between those who survived and who deceased in sepsis." (PMID 36631486, 2023). "Accordingly, its role was studied in kidney injury due to a variety causes, but, to our surprise, we could not find data in the literature about the kinetics of urine MIF in sepsis and its association with sepsis-related kidney injury." (PMID 36631486, 2023). "In addition, MIF has been shown to be a potential biomarker and therapeutic target in sepsis." (PMID 38275363, 2023). "Since the urine MIF level in sepsis survivors was higher than that of deceased patients in the present study, it can be speculated that the endogenous renoprotective effect of renal MIF was attenuated in the nonsurvivor group, thereby indicating the increased severity of the disease." (PMID 36631486, 2023). "Beyond this background, MIF seems to be a good candidate marker to be evaluated in HFpEF since it was shown to be a marker for oxidative stress, organ fibrosis, cell damage, atherosclerosis, lung disease, rheumatic diseases, sepsis, severe illness, and chronic kidney disease." (PMID 29728137, 2018). "Thus, targeted removal of MIF from the circulating blood pool might be a promising approach to reduce mortality in severe sepsis." (PMID 27313864, 2016).
Sepsis (continued). "Macrophage migration inhibitory factor (MIF) is a widely-expressed and versatile cytokine that plays key roles in several pain and inflammatory diseases, including neuropathic pain, rheumatoid arthritis, atherosclerosis, asthma, sepsis, and bladder inflammation." (PMID 26020638, 2015). "MIF is induced in a broad range of oxidative stress conditions and the resulting inflammation that develops as a result of certain types of pathological conditions such as sepsis, rheumatoid arthritis, inflammatory bowel disease, hepatitis and pulmonary disease." (PMID 26412311, 2015). "In the 1990s, sepsis was believed to be associated with an exacerbated release of mainly proinflammatory cytokines, such as tumor necrosis factor (TNF-α), interleukin (IL-1, IL-6, and IL-12), interferon-γ (IFN-γ), and macrophage migration inhibitory factor (MIF)." (PMID 25614712, 2014). "Therefore, we examined whether neutrophil infiltration and MIF expression are involved in the cardioprotective effect of HS in a conscious rat model of LPS-induced sepsis." (PMID 24371817, 2013). "In addition, TNF-α and IL-1 amplify inflammatory cascades in an autocrine and paracrine manner by activating macrophages to secrete other proinflammatory cytokines (IL-6, IL-8, and MIF), lipid mediators, and reactive oxygen and nitrogen species, leading to sepsis-induced organ dysfunction." (PMID 23853427, 2013). "This is in line with a recent study among pediatric and adult patients with severe sepsis or septic shock caused predominantly by Neisseria meningitides and other gram-negative bacteria in which elevated MIF levels were shown to be predictive of early mortality." (PMID 20169062, 2010). "In summary, our results suggest that substances involved in the redox homeostasis (e.g., TRX1, MIF) represent central hubs in the septic inflammatory response, as assessed by significantly elevated plasma levels of these mediators in patients with severe sepsis or septic shock." (PMID 20847814, 2010). "Serum MIF could be a valuable clinical marker of adrenal insufficiency in sepsis patients." (PMID 20021698, 2009). "In addition, plasma concentration of MIF is positively correlated with the severity of sepsis." (PMID 19413900, 2009). "Therefore, serum MIF and GC might be indicators of the inflammatory/anti-inflammatory balance in sepsis patients." (PMID 20021698, 2009). "MIF inhibitors reduced the effects of CSN6 on inflammation and ferroptosis in an in vitro sepsis model." (PMID 40595050, 2025). "Epidemiologic and experimental evidence suggests an important role for MIF in infectious and para-infectious heart conditions, including Chagas disease, rheumatic heart disease (RHD), sepsis, and viral-mediated heart diseases." (PMID 40092999, 2025). "Conversely, in the sepsis group, the probability of cellular communication between NKT and CD16Mono via MIF - (CD74+CXCR4) exhibited the highest magnitude." (PMID 40375981, 2025). "The first small molecule inhibitor of MIF, ISO-1, provided proof of concept for significantly increasing the survival of mice with sepsis, reducing disease severity in mouse models of SLE, and delaying onset in a mouse model of autoimmune diabetes." (PMID 40092999, 2025). "The mean serum levels of TNF-α, MIF, TLR4, and 8-epi-PGF2α levels were significantly higher in the sepsis and vehicle groups than in the normal and sham groups." (PMID 39144689, 2024). "Compared to both the vehicle and sepsis groups, a single dose of ghrelin administered immediately after the CLP procedure significantly lowered serum MIF levels (P <0.001)." (PMID 39144689, 2024). "With regards to the prediction performance of fatal outcome in sepsis, the AUROC was found to be 0.79 for MIF and 0.68 for IL-672." (PMID 36631486, 2023). "Compared to the sham group, the sepsis group had significantly elevated levels of TLR-4, IL-6, TNF-α, MIF, F2-isoprostane, caspase-3, cTn-I, and CK-MB (p<0.05)." (PMID 37900081, 2023).